CRP (C-reactive protein)
Diseases named in the same sentence as CRP in open-access papers (continued):
Sharing a sentence is not in itself a finding about the gene and the disease.
diabetes (continued). "Another scoring system based on age ≥ 70, need for oxygen supply at admission, diabetes, chronic kidney disease, dementia, CRP > 4 mg/dL, and infiltration observed in the chest X-rays at the initial diagnosis has a 98.4% negative predictive value, but only 35.8% positive predictive values." (PMID 38391586, 2024). "Stratified analyses showed such positive associations between dietary Mg and ASMI were consistent across different strata of gender, age, PIR, BMI, physical activity, diabetes, heart disease, chronic kidney disease, energy intake, CRP, serum albumin, and the use of muscle-related medications." (PMID 38509619, 2024). "Those with higher CRP levels were usually older, female, married, non-Hispanic White, some college or AA degree, drinkers, a decreased risk of diabetes and hypertension, and obese." (PMID 39969369, 2024). "In addition, Chinese patients with RA had a significantly higher level of CRP but lower level of BMI, as well as a lower prevalence of active smoking, hypertension, diabetes, dyslipidemia and cardiovascular diseases than their US counterparts." (PMID 39713142, 2024). "CRP is a complex, multifactorial phenotype influenced by both non-genetic/environmental factors such as age, sex, diabetes, systolic blood pressure, smoking, socioeconomic status, and BMI and genetic factors such as CRP locus alleles." (PMID 39596582, 2024). "Consequently, the clinical-radiomics nomogram was established using multivariate logistic regression, incorporating diabetes mellitus, splenomegaly, cryptogenic liver abscess, CRP level, and a Rad-score." (PMID 39392039, 2024). "After adjusting for potential confounding factors (age, gender, smoking, diabetes, hypertension, creatinine, uric acid, hs-CRP), TC marginal high (OR: 1.68, 95% CI: 1.05–2.69, P = 0.031) or high (OR: 1.92, 95% CI: 1.25–2.95, P = 0.003) was positively correlated with CAD severity." (PMID 37441702, 2023). "Interestingly IVDD, shares many degenerative and inflammatory aspects of disease with type 1 diabetes mellitus, disc herniation, and osteoarthritis including up regulation of CRP." (PMID 37756062, 2023). "As anticipated, a majority of clinical risk factors such as age, BMI, waist circumference, serum triglycerides (TG), TC and HDL, C-reactive protein (CRP), and history of diabetes mellitus showed significant differences between individuals with and without hypertension." (PMID 38137595, 2023). "Furthermore, diabetes mellitus, C-reactive protein, lymphocyte count, red blood cell width distribution, as well as mean red blood cell volume, are not included as predictors in the APACHE II model." (PMID 37635161, 2023). "For example, in adult women without a history of breast cancer and diabetes, time restricted eating regimens were associated with improved glucoregulation, lower glycated haemoglobin (HbA1c) levels, and lower C-reactive protein (CRP) levels." (PMID 36422754, 2023). "The levels or probabilities of variables such as age, sex, smoking, hypertension, diabetes, hypotensive drugs, hypoglycemic drugs, BMI, TG, HDL-C, HB, PLT, ALT, TBIL, eGFR, CRP, HbA1c, all-cause death and cardiovascular death were significantly different among the four groups of SUA." (PMID 38192419, 2023). "One possible explanation is that we included only CRP as a proxy for inflammatory indicators, while multiple biological pathways could influence the relationship between sedentary behavior and diabetes." (PMID 38075044, 2023). "In addition, the incidence of diabetes and hypertension, as well as the concentrations of TC, CRP, and SAA were higher in CHD patients." (PMID 37441706, 2023). "Low levels of CRP were only observed in frail patients with diabetes." (PMID 36732827, 2023). "With regards to models predicting incident diabetes/high blood glucose and CHD, all combinations of wealth and CRP were associated with increased hazard of incident disease relative to those with high wealth and low CRP." (PMID 37808231, 2023).
diabetes (continued). "However, advanced statistical analyses revealed statistically significant correlations between age, hs-CRP, coronary heart disease and diabetes in men." (PMID 37835888, 2023). "The subjects who reported three or more times nocturnal voiding were more likely to experience obesity, hypertension, and diabetes as well as had greater levels of total blood cholesterol, triglycerides, and serum CRP compared with those who reported fewer nocturia episodes." (PMID 38186694, 2023). "Thus, the C-reactive protein/albumin rate is elevated in inflammatory conditions like diabetes and its microvascular complications." (PMID 37370958, 2023). "Regarding the components of MAFLD, we observed a positive correlation of the overall metals mixture with diabetes, overweight/obesity, metabolic dysfunction, central obesity, prediabetes, insulin resistance, high C-reactive protein (CRP), and high triglyceride (TG)." (PMID 36950101, 2023). "In the subgroup with normal cognitive function, patient demographics, laboratory data, and comorbidities (age, education, diabetes, hemoglobin, albumin, CRP, CAS percentage, Ccr, LVMI, and LVH percentage) were significantly different compared with the CI group." (PMID 36890445, 2023). "Multivariable regression analysis confirmed diabetes mellitus (p < 0.001, HR 7.096, CI 0.95% 3.098–16.253) as the strongest predictor for lethal outcome followed by CRP (p < 0.022, HR 1.009, CI 0, 95% 1.001–1.016) and ferritin level (p < 0.013, HR 1.001, CI 0.95% 1.000–1.002)." (PMID 38034537, 2023). "Similarly, oral trimetazidine (20 mg three times a day) among volunteers with diabetes and idiopathic dilated cardiomyopathy maintained CRP levels stable over 6 months compared to a placebo control that showed increased CRP." (PMID 37386057, 2023). "This outcome was verified after controlling for established demographic, clinical and laboratory factors and biomarkers of HF survival, including N-terminal pro b-type natriuretic peptide, HSP, MPO, CRP, creatinine, history of diabetes and more, in all three groups of patients." (PMID 37512127, 2023). "Meanwhile, age, stroke, renal insufficiency, diabetes, WBC and CRP might be related to 1-year mortality, and age, diabetes, WBC, D-dimer and CRP were potential confounding factors for 3- and 5- year mortality." (PMID 36860689, 2023). "In the third model, we additionally adjusted the second model for potential confounders which could also acts as mediators, including serum cholesterol, serum C-reactive protein, body mass index, hypertension, and diabetes mellitus." (PMID 37441475, 2023). "However, the association remained significant after adjusting for BMI, serum albumin, CRP and comorbidity of diabetes and cardiovascular diseases." (PMID 37696942, 2023). "Patients who had previously developed Covid-19 needed hospitalization in high percentage (84%); this group showed significantly higher prevalence of diabetes mellitus than Covid-19-free PE patients, reduced serum levels of C-reactive protein, sST2 and PESI score." (PMID 37537404, 2023). "In multiple regression analysis, serum magnesium levels were independently associated with increased CFS scores (β = − 0.126, P = 0.005) adjusted for age, body mass index, diabetes, cardiovascular diseases, prevalent fractures, serum albumin and C-reactive protein." (PMID 37696942, 2023). "The extent to which observed associations between high-sensitivity C-reactive protein (hs-CRP) and incident diabetes are explained by obesity and hypertension remains unclear." (PMID 37775289, 2023). "IL-6 could be better marker than CRP for the inflammation seen with diabetes and even in co-morbidity, more so as IL-6 could differentiate good from poor glycemic control." (PMID 37545969, 2023). "Unadjusted and adjusted for age, BMI, race, sex, history of CKD, HTN, liver disease, diabetes, reported pneumonia, antibiotic use, and blood CRP, WBC, as well as lactate levels did not weaken the risk associations." (PMID 37068086, 2023).
diabetes (continued). "Age, sex, diabetes mellitus, serum albumin, systolic blood pressure, smoking history, uric acid and time stratified eGFR, log(urine protein creatinine ratio), total cholesterol, C- reactive protein." (PMID 36715437, 2023). "Furthermore, we performed subgroup and interaction analyses based on gender, race, PIR, health insurance, smoking, alcohol consumption, diabetes, hypertension, cancer, and CRP." (PMID 37893796, 2023). "Even when adjusted for demographics, diabetes, pneumonia, antibiotic use, white blood cell count, and serum C-reactive protein levels, the risks remained relatively high for mechanical ventilation (HR, 1.80, 95%CI: 1.67–1.94) and death (HR, 1.76, 95%CI: 1.66–1.87)." (PMID 37068086, 2023). "In addition, they found that OPG levels correlated positively with age, female sex, CRP, and diabetes status, but negatively with statin use." (PMID 37388640, 2023). "In the present cohort, obesity-linked variables, such as diabetes, dyslipidemia (low HDL cholesterol and high triglyceride levels) and elevations in systemic inflammatory markers (CRP, IL-6 and IL-18), were more common among individuals with complete fatty degeneration of thymus." (PMID 37653480, 2023). "After adjustment for potential confounders, age (OR=1.094, P <0.001), female sex (OR= 3.44, P =0.005), diabetes (OR=3.756, P =0.008), CRP (OR=1.09, P =0.015), serum magnesium (OR=0.755, p=0.042) and BMI (OR=0.701, P <0.001) were independently associated with sarcopenia." (PMID 37265691, 2023). "In diabetes mellitus, increased production of CRP by hepatocytes has been reported." (PMID 37759824, 2023). "Similarly, the increase in the concentration of inflammatory markers (such as CRP) is also involved in the occurrence and progression of long-term macrovascular complications in diabetes." (PMID 36814226, 2023). "Compared to participants without MetS, those with MetS were older (p< 0.001), had higher rates of smoking (p< 0.001) and alcohol consumption (p< 0.001), higher CRP values (p< 0.001), and family histories of diabetes, hypertension, and stroke (p< 0.001) in both sexes." (PMID 38144566, 2023). "In addition, it has been well established that the presence of chronic diseases, such as diabetes and hypertension, can increase serum CRP levels." (PMID 37823095, 2023). "There were negative associations between smoking and QA; between diabetes and KA/XA ratio; and between CRP and KA/QA ratio." (PMID 36986451, 2023). "Previous studies have confirmed that the level of cellular inflammatory factors such as tumor necrosis factor-α (TNF-α), interleukin-6 (IL-6) and C-reactive protein (CRP) was increased in elderly patients with diabetes, and anti-inflammatory factors such as IL-10 were reduced." (PMID 38273819, 2023). "Sleep duration may be involved in the pathogenesis of CCVD, as numerous studies have suggested the relationship between sleep duration and obesity, diabetes as well as increased levels of CRP." (PMID 37003977, 2023). "CRP levels were significantly elevated in diabetes and HIV co-morbidity compared to other groups." (PMID 37545969, 2023). "Those with diabetes have increased systemic levels of CRP, a protein in the blood." (PMID 37894687, 2023). "Survival of AAA patients following EVAR may be influenced by age, some inflammatory biomarkers such as white blood cell (WBC) and C-reactive protein (CRP), and comorbidities like diabetes, renal insufficiency and stroke." (PMID 36860689, 2023). "In multivariate models that adjusted for age, BMI, diabetes, cardiovascular diseases, prevalent fractures, serum albumin, and CRP, which were variables with P < 0.05 in univariate analyses, serum magnesium levels were independently associated with increased CFS scores (β = − 0.126, P = 0.005)." (PMID 37696942, 2023).
diabetes (continued). "Erythrocyte sedimentation rate and CRP were measured in patients with hepato-splenomegaly, high blood pressure, diabetic mellitus with polyneuropathy, oral cavity infection, and other conditions of unknown etiology." (PMID 37860004, 2023). "The biomarkers NLR, AST, WBC, CRP, and BUN, among the clinical symptoms of anorexia, respiratory distress, and chest pain and the underlying diabetes, chronic nervous disorders, and also variables such as age, hospitalization in ICU, and PO2, had a positive significant relationship with LOHS." (PMID 37415112, 2023). "After adjusting for age, smoking, diabetes mellitus, blood pressure, and hormonal replacement therapy, ascending quintiles of CRP showed relative risks (RR) of 1.4, 1.6, 2.0, and 2.3 (p < 0.001) for a first cardiovascular event, compared to the lowest quintile." (PMID 37760885, 2023). "Experimental evidence found that patients with diabetes have chronic low-grade inflammation marked by higher levels of pro-inflammatory mediators including C-reactive protein, interleukin 6, and tumor necrosis factor alpha, as well as abnormal cytokine-secreting cells." (PMID 37478111, 2023). "On the other hand, CRP, a clinically used biomarker of inflammation was elevated in the total cohort and was significantly higher in adults with periodontitis and concomitant diabetes." (PMID 38201914, 2023). "This study aimed to investigate the utility of carcinoembryonic antigen (CEA), C-reactive protein (CRP), serum albumin level, hemoglobin, and lactate dehydrogenase (LDH) as biomarkers for cancer risk, and the biological implications of diabetes on the evolution and prognosis of oncological patients." (PMID 37627906, 2023). "Moreover, CVD groups with diabetes had higher CRP levels than the corresponding normoglycemic groups." (PMID 35997998, 2023). "Similarly, the addition of liraglutide to insulin treatment in obesity and diabetes patients resulted in significant reductions in CRP concentration after three months of treatment." (PMID 37760885, 2023). "Additionally, chronic elevation of CRP is prevalent in multiple inflammatory comorbidities, including diabetes and cardiovascular diseases." (PMID 38002515, 2023). "Thus, the group with diabetes had higher CRP concentrations at equivalent BMIs (and weights) to those without diabetes." (PMID 37891943, 2023). "Participants with diabetes had significantly higher C-reactive protein (CRP) concentrations, with the median value being in the high clinical risk category, i.e., >3 mg/L, as well as a higher percentage of HbA1c, and fasting blood glucose and fasting insulin concentrations (p < 0.0001)." (PMID 37891943, 2023). "Sarcopenia alone patients were older and had higher CRP levels and rates of diabetes." (PMID 37265691, 2023). "Each unit of RC was associated with an 8.7% increase in stroke risk after adjusting for BMI, gender, age, drinking status, physical activity, heart diseases, diabetes mellitus, hypertension, lipid therapy, smoking status, CRP, Scr, and Cystatin C in Model 3 (HR = 1.087, 95%CI: 1.001–1.180)." (PMID 37880769, 2023). "The univariate logistic regression analysis demonstrated that male, BMI, heart failure, diabetes, larger LAD, higher serum levels of CRP, PNI < 46.4 and GNRI < 105.7 were significantly associated with higher incidence of LAT, while higher PNI and GNRI were associated with lower risk." (PMID 37891483, 2023). "Furthermore, there is an association between AS and atherosclerosis risk factors—age, sex, smoking, diabetes mellitus, hypertension, elevated low-density lipoproteins, (LDL), reduced high-density lipoproteins (HDL), and increased C-reactive protein (CRP)." (PMID 36768515, 2023). "Microalbumin, Urine Albumin to Creatinine Ratio and C-reactive protein levels mirrored the fasting plasma glucose levels, being substantially higher among in men and women in Class 3, characterised by diabetes, indicating adverse renal function and inflammation." (PMID 36342918, 2022).
diabetes (continued). "The FGF-21 level was independently associated with aortic stiffness (odds ratio (OR): 1.008; 95% CI: 1.003–1.012; P=0.001) after adjusting for diabetes mellitus, age, hypertension, C-reactive protein, and body weight in multivariable logistic regression analysis." (PMID 35186330, 2022). "This is the first study from North India to compare the inflammatory cascade (CRP, Endocan and Perfusion Index) of dengue patients associated with and without diabetes." (PMID 36268329, 2022). "Adjusting for age, sex, smoking status, BMI (or weight for traits indexed by height), antihypertensive treatment, diabetes status, TC/HDL, and SBP (except when evaluating PP), we observed positive associations of HbA1c, BMI, PP, CRP, HR, TC/HDL, LVMI, and gait with HF risk." (PMID 35617332, 2022). "The limited evidence suggested that it is related to chronic inflammation markers, such as C-reactive protein, and predicted cardiovascular events and all-cause mortality in patients with or without diabetes." (PMID 36079889, 2022). "Overweight, smoking, hypertension and diabetes were more common in the High CRP group (p < 0.05)." (PMID 35707008, 2022). "Positive associations with NT-proBNP were observed for CRP, systolic blood pressure, no physical activity, diabetes mellitus, smoking and coronary artery calcification." (PMID 36114409, 2022). "Circulating levels of CRP could be influenced by age, obesity, sex, smoking, diabetes, and use of medications summarily." (PMID 36448063, 2022). "As some variables are known to be associated with PhA, such as age, sex, diabetes, glomerular filtration rate, BMI, hemoglobin, physical activity, calcium x phosphorus, PTH, and ultrasensitive CRP a hierarchical multiple logistic regression was performed to predict positive CAC score." (PMID 35990362, 2022). "There have been many studies demonstrating an association between CRP and IL-6 and incident diabetes, and several reported this to be independent of adiposity or insulin resistance." (PMID 36407366, 2022). "Previous studies suggested that factors associated with the length of hospital stay were age >60 years, diabetes, fever, neutrophil and lymphocyte count, hypocalcemia, hypochloremia, increased CRP and D-dimer concentrations, bilateral pneumonia, and steroids administration." (PMID 35230008, 2022). "The distribution of poverty to income ratio, marital status, C-reactive protein, coronary heart disease history, diabetes history, and stroke history in Q1–Q4 of serum triglycerides showed no statistical difference with approximate similarities (p values > 0.05)." (PMID 35405939, 2022). "Stratified analyses indicated that the negative relationship of the total testosterone with all-cause death risk was independent of factors involving age, race, body mass index, diabetes, hypertension, C-reactive protein, creatinine, and sex hormone binding globulin." (PMID 36124237, 2022). "The global CT score, age, CRP, and diabetes were independent predictors of in-hospital mortality." (PMID 36004961, 2022). "After the univariate analysis for severe respiratory failure, significant variables (age, sex, diabetes mellitus, dyslipemia, arterial hypertension, previous thrombosis, elevated ferritin, elevated CRP and elevated D-dimer) were included in a binary logistic regression analysis with aPL." (PMID 35812410, 2022). "A better understanding of CRP signaling pathways may help discover therapies for diabetes and cardiovascular complications." (PMID 35178206, 2022). "Thus, elevated plasma CRP concentrations are found in smokers, those with atherosclerosis, psychological stress, diabetes, or obesity, and older adults." (PMID 36457873, 2022). "According to previous reports, the plasma levels of T decrease rapidly and reach a minimum level on the first day of onset of symptoms, and inversely correlate with plasma CRP levels, degree of coronary atherosclerosis, BMI, and prevalence of diabetes mellitus." (PMID 36199650, 2022).